FGFR3 (fibroblast growth factor receptor 3)
Diseases named in the same sentence as FGFR3 in open-access papers (continued):
Sharing a sentence is not in itself a finding about the gene and the disease.
tumor (553 papers, 2003 to 2026). "Loss of this variant leads to constitutive FGFR3 pathway activation, thereby promoting tumor cell proliferation and resistance to apoptosis." (PMID 41584352, 2026). "In bladder cancer, common alterations like FGFR3-TACC3 fusions and gain-of-function mutations (e.g., S249C, R248C) lead to hyperactivation of FGFR3 signaling, promoting tumor growth and progression." (PMID 40943615, 2025). "Detecting an FGFR3 expression signature in tumor samples can serve as a potential diagnostic and prognostic marker, guiding treatment decisions." (PMID 40938919, 2025). "B cell secretion of IGF1 then causes tumor cells to activate FGFR3 signaling and adopt stem-like properties." (PMID 40663561, 2025). "Mechanistic studies further revealed that the exosomal miR-152-3p/FGFR3 axis was implicated in angiogenesis and tumor progression in vitro and in vivo." (PMID 40075158, 2025). "These challenges are compounded by tumor heterogeneity, variability in antigen expression, and discrepancies in FGFR3 mutational status." (PMID 39857670, 2025). "Intriguingly, we observed an apparent increase in tumor mutational burden across the FGFR3/HRAS, FGFR3 & chr9Del, GI, and AA-like subtypes." (PMID 40247187, 2025). "In the assessment of tumor recurrence, FGFR3 alterations were significantly associated with shorter RFS." (PMID 39410541, 2024). "We first show how the response to ICI monotherapy depends on the tumor composition–both antigenicity and FGFR3 mutation status–and the resulting immune infiltrate." (PMID 38515743, 2024). "They indicated that other genes, TERT and FGFR3, were most closely associated with tumour recurrence." (PMID 39768623, 2024). "FGFR3 gene mutations have been found to be highest in BC and are associated with cancer cell proliferation and migration, and tumor invasiveness." (PMID 39559360, 2024). "RAS or FGFR3 mutation, found in Ta tumors, are mutually exclusive and associated with low tumor grades and stages." (PMID 39001362, 2024). "With a heterogeneous population with regards to the FGFR3 mutation, low proliferation rates of FGFR3 mutants results in a situation in which ICI monotherapy results in at least 90% reduction in tumor burden on Day 25 relative to control." (PMID 38515743, 2024). "Few studies have examined FGFR3 mutational status and expression levels in different parts of the same tumor sample or in paired samples of primary and metastatic tumors from the same patient." (PMID 39031286, 2024). "The incidence of FGFR3 alterations or mutations vary, depending on tumor stage, and occur in up to 80% of stage Ta tumors and are associated with favorable outcomes In stage T2 and greater tumors, FGFR3 mutations are less common (10–20%)." (PMID 38675715, 2024). "As a prognostic biomarker of UC, FGFR3 mutations are generally associated with a less aggressive tumor and favorable prognosis." (PMID 38592174, 2024). "Compared to monotherapy, JNJ-42756493 (FGFR inhibitor) plus AZD8055 or siolimus (mTOR inhibitor) has a more significant anti-tumor effect in organoids with FGFR3 mutations and nonsense TSC mutations." (PMID 39022082, 2024). "We find that even a small population of weakly antigenic tumor cells bearing an FGFR3 mutation can render the tumor resistant to combination therapy." (PMID 38515743, 2024). "Our model quantifies how tumor antigenicity and FGFR3 activating mutations impact disease trajectory and response to anti-PD-1 antibodies and anti-FGFR3 SMI." (PMID 38515743, 2024). "Significant pairwise dependency was found between tumor stage, FGFR3 mutation status and PD-L1 expression (p < 0.01)." (PMID 37151354, 2023). "In vivo, the treatment of trastuzumab-resistant murine models with a selective inhibitor of FGFR3 was associated with a reduction in tumor burden and an increase in overall survival (OS) compared to control." (PMID 36983691, 2023). "The tumor from Pt#5 with luminal differentiation harbored an FGFR3 mutation, as expected for this molecular subtype." (PMID 38098507, 2023).
tumor (continued). "As expected, the IHC scores of Fgfr3 and Fgfr4 were decreased in Kdm6a‐deficient tumour tissues, confirming that FGFR3 and FGFR4 expression was positively associated with KDM6A expression." (PMID 37846441, 2023). "The aim of our study was to demonstrate the frequency of FGFR3 mutation in different tumor stages of cystectomy samples, and to reveal a possible relationship between the FGFR status, PD-L1 status, CPS score, tumour-stages and the survival of patients." (PMID 37151354, 2023). "The high necroptosis phenotype (Cluster B) was characterized by a higher abundance of tumor immunosuppressive cells and more key biological processes driving tumor progression, while the low necroptosis group (Cluster A) had higher FGFR3 mutations." (PMID 37000317, 2023). "That study also found a relationship between FGFR3 mutations and the stage and grade of UC, with the frequency of FGFR3 mutations decreasing with increasing tumor stage and grade." (PMID 37924117, 2023). "FGFR3 mutations are primarily associated with lower tumor grades and stages in uroepithelial bladder cancer, and patients with FGFR3 mutations generally have a better clinical prognosis." (PMID 37283287, 2023). "Such correlation with poor prognosis was also observed in EPN in which FGFR3 was associated with shorter overall survival and shorter time to tumor recurrence." (PMID 36839989, 2023). "Among those, only PIK3CA and FGFR3 mutations were already detectable in primary tumor tissues in 2/14 and in 2/2 samples respectively." (PMID 37064137, 2023). "Specifically, only FGFR3 mutation had been already detected in primary tumor tissues, while PIK3CA was acquired in 28% of cases." (PMID 37064137, 2023). "FGFR3 mutations from the most infiltrative areas of the tumor were analyzed by targeted next-generation sequencing and PD-L1 (28-8 DAKO) tests (tumor positive score -TPS and combined positives score–CPS)." (PMID 37151354, 2023). "Simultaneously, mutation of gatekeeper residue (V555M) of FGFR3 can be the reason for resistance, as shown in human tumor cell lines." (PMID 35326568, 2022). "Our class C tumours mostly fall (20 of 24; 83%) within UROMOL classes 1 and 3; our class C and UROMOL classes 1 and 3 are characterised by FGFR3 mutations and/or high FGFR3 gene expression and low tumour grade/stage." (PMID 35655252, 2022). "Here, we performed a comprehensive bioinformatic analysis utilizing transcriptome RNA-seq data and somatic mutation data and we found that the decreased expression of FGFR3 correlates with tumor metastasis." (PMID 35991125, 2022). "According to GSEA, the biological process involving tumor cell metastasis was highly linked with the group with low FGFR3 expression." (PMID 35991125, 2022). "For example, FGFR3 was enriched greater than 8x in tumor-positive samples, while PIK3CA mutation and FGF3 amplification were never observed in post resection, negative surveillance cystoscopy samples." (PMID 36233691, 2022). "FGFR3 mutations occur in urothelial hyperplasia of the bladder and are thought to be associated with tumor formation in NMIBC10." (PMID 36198773, 2022). "FGFR3 is also clinically significant, whose mutations have been identified as a key to tumor initiation." (PMID 33407469, 2021). "The results suggest that FGFR3 mutation can lead to increased tumor volume primarily due to either proliferation or survival effects—depending on the relative strengths of these signaling pathways, that is, the parameters." (PMID 34984415, 2021). "Abnormal FGFR3 signaling due to overexpression and/or mutation induces tumor proliferation and metastasis in multiple tumors." (PMID 34207911, 2021). "That is, while anti-PD-L1 antibody loses efficacy when the FGFR3 mutation is active, anti-PD-L1 antibody impact on tumor reduction is recovered when combined with a drug that targets FGFR3." (PMID 34984415, 2021). "For patients with an FGFR3 mutant tumor, surveillance by FGFR3 mutation analysis was proposed as a potentially viable choice." (PMID 34884669, 2021).
tumor (continued). "FGFR3 is a receptor tyrosine kinase that mutates to become constitutively active and drive tumor growth through activation of downstream MAPK and/or Pi3K pathway signaling." (PMID 33799514, 2021). "In the UROMOL cohort, wild-type FGFR3 was associated with tumours infiltrated by immune cells, which is in line with other studies." (PMID 34934968, 2021). "These clones will compromise specificity for ctDNA detection unless focusing solely on disease-restricted hotspot mutations (e.g., in FGFR3) or mutations defined from prior tumor tissue testing." (PMID 33420073, 2021). "NMIBC is molecularly characterized by activating fibroblast growth factor receptor 3 (FGFR3) mutations, which are present in 20–80% of patients, depending on tumor stage." (PMID 33799514, 2021). "Results: high grade primary luminal NMIBC showed comparatively higher expression of PD-L1 and microRNA-145 than a low grade tumor, whereas the latter had a higher FGFR3 expression and hotspot mutation rate." (PMID 33238591, 2020). "We also showed that hotspot mutations of TERT promoter and FGFR3 are frequently identified in tumor tissues of Japanese UBC patients consistent with those in previous report in Western countries." (PMID 32509577, 2020). "One can discuss if FGFR3 p.R248C mutations are associated with more aggressive tumors, since it is particularly enriched in this subset of tumors and associated with larger tumor size in a univariate analysis." (PMID 32023888, 2020). "Most of the FGF9‐positive HCC exhibited also elevated levels of FGFR3‐IIIb or FGFR3‐IIIc mRNA causing that 82% of the tumours with overexpression of FGF9 also showed upregulated FGFR3‐IIIb and/or FGFR3‐IIIc." (PMID 32378800, 2020). "In the BCG-NMIBC cases a statistically significant association between tumor size and FGFR3 p.R248C mutations was found (p = 0.048)." (PMID 32023888, 2020). "The Uromonitor test kit (U-Monitor, Porto, Portugal) is a procedure developed and optimized for the detection of hotspot mutations in TERTp and FGFR3 genes in DNA from tumor cells exfoliated to urine in a real-time PCR platform." (PMID 31941070, 2020). "In summary, the high expression of FGF2 was related to the tumor size of ESCC tissues and lymph node metastasis; the FGFR3 expression was associated with tumor differentiation, race, and lymph node metastasis." (PMID 33381388, 2020). "FGFR3 overexpression or active mutation promotes tumor cell proliferation, survival, and drug resistance." (PMID 33584313, 2020). "At the same time, other studies have shown that a FGFR3 mutation suppressed acute inflammation, causing immune cells (mainly neutrophils) to behave aberrantly in tumors, thereby causing tumor progression." (PMID 33117683, 2020).
tumor (continued). "It has been observed that there was significant correlations between mutated FGFR3 and lower tumor stage/grade." (PMID 32795296, 2020). "In the present study, we evaluated FGFR3 mutational status, PD-L1 tumor cell and immune cell expression and the molecular subtype in a cohort of 25 LNUCs." (PMID 32213857, 2020). "One of the most studied among these genes is fibroblast growth factor receptor 3 (FGFR3), mutations of which are found in almost 80% of the low-grade tumours and associated with a good prognosis." (PMID 32664878, 2020). "Tumor grade in association with PD-L1 and FGFR3 expression can be considered a complex predictor for primary luminal NMIBC progression." (PMID 33238591, 2020). "Conclusions: tumor grade in association with PD-L1 and FGFR3 expression can be considered as a complex predictor for primary luminal NMIBC progression." (PMID 33238591, 2020). "Their results indicated that FGFR3 mutations were more frequently observed in neoplasms with low malignant potential, at 77%, and in tumors TaG1, at 61%, and TaG2, at 58%, than in tumors TaG3, at 34%, and T1G3, at 17%." (PMID 32397531, 2020). "In two tumours, FGFR3 S249C mutations were detected, and both tumours were negative for RAS mutations and HPV infection." (PMID 31960612, 2020). "In the BCG-NMIBC cases wild type and mutated for FGFR3, a statistically significant association between tumor size and FGFR3 p.R248C mutation was found (p = 0.048)." (PMID 32023888, 2020). "The high expression of FGFR3 was associated with tumor differentiation (p = 0.043 and p < 0.05), lymph node metastasis (p = 0.078 and p < 0.1), and race (p = 0.033 and p < 0.05)." (PMID 33381388, 2020). "The tumor grade (HR = 571.72 [11.03–2.96] p = 0.002), PD-L1 expression (HR = 2.33 [0.92–1.92] p = 0.012), and FGFR3 expression (HR = 0.08 [0.17–0.42] p = 0.003) were associated with relapse-free survival." (PMID 33238591, 2020). "Overexpression of fibroblast growth factor receptor 3 (FGFR3) has been linked to tumor progression in many types of cancer." (PMID 31619201, 2019). "First, we detected the expression levels of and potential mutations in FGFR3 in the first 12 tumour specimens and pairs of adjacent tissues from MIBC patients." (PMID 30999937, 2019). "Subsequently she was enrolled to a phase II study and received AZD4547 due to an actionable mutation at FGFR3 found in tumor biopsy." (PMID 30820365, 2019). "Actually, it has been well-known that FGFR3 is one of the most frequently mutated genes in BC and is more frequent in lower tumor stage, with over 65% of NMIBC and about 15% of MIBC bearing an FGFR3 mutation." (PMID 30697528, 2018). "Patients displaying a combined overexpression of FGFR3 and Ki67 showed an approximately four-fold higher risk for tumor progression (multivariate hazard ratio (HR): 3.943, 95% CI: 1.247 to 12.466, p = 0.019)." (PMID 30154342, 2018). "As the majorities of studies analyzed samples from muscle-invasive cancer, the association between FGFR3 fusion and tumor grade or stage is still uncertain." (PMID 30064409, 2018). "This study provides a novel insight into the tumour‐promoting effect of FGFR3 mutations via regulation of inflammation at the pre‐tumour stage in the bladder." (PMID 30043421, 2018). "To more deeply investigate the role of CDKN2A expression in tumour prognosis and its association with drug target genes like FGFR3, we performed qRT-PCR expression profiling and reanalysis of existing CDKN2A and FGFR3 RNA expression data of MIBC after RC." (PMID 30258198, 2018). "When subtypes were grouped together, human urothelial‐like/luminal tumours with FGFR3 mutation were less immune‐infiltrated than those with wild‐type status." (PMID 30043421, 2018). "The superior anti-tumor activity of tubacin was linked to its ability to not only inhibit accumulation of mutant FGFR3, but also to cause robust downregulation of MYC and cyclin D1, and to induce a DNA damage response and apoptosis." (PMID 29423038, 2018).
tumor (continued). "At 20 weeks, only tumour pathogenesis was associated with the FGFR3 genotype, and inflammation was associated with tumour progression." (PMID 30043421, 2018). "A better understanding of the role of FGFR3 mutations in tumour pathogenesis and progression will help in interpreting trial outcomes and allow further stratifications." (PMID 30043421, 2018). "Statistical analyses of correlation showed that while initial bladder phenotypes in morphology and inflammation were FGFR3‐dependent, increased levels of inflammation were associated with tumour progression at the later stage." (PMID 30043421, 2018). "We also validated in vivo the critical role of p38 in mutated FGFR3‐induced tumor growth, by showing that p38 inhibition with SB203580 significantly slowed the tumor growth of MGH‐U3 and RT112 xenografts in athymic nude mice." (PMID 29463565, 2018). "FGFR3 expression and Ki67 index correlated with tumor grading (FGFR3: p < 0.001, Ki67: p < 0.001), but only FGFR3 expression was significantly associated with tumor stage (FGFR3: p < 0.001)." (PMID 30154342, 2018). "Moderate-to-strong FGFR3 staining was more frequently observed among pediatric patients than among adults, but only the association between FGFR3 and tumor location remained significant in the pediatric cohort." (PMID 28468611, 2017). "It is indeed intriguing that tumours with FGFR3 mutations or overexpression as per previous classification, show an increased overall survival, which contradicts the underactive immune state observed here." (PMID 29050337, 2017). "We also noted associations of several cancer driver mutations in genes such as PIK3CA, BRAF, RAS family members, and FGFR3, with estimates of immune infiltrate, although these associations were often observed in limited tumor types." (PMID 28749946, 2017). "The FGFR3 F386L polymorphism has been reported in association with low-grade tumours and early disease stage in prostate cancer." (PMID 28304377, 2017). "Further investigations showed that FGFR3 mutations occurred at a much higher rate in BC than in other tumor types (e.g., cervix, multiple myeloma, gastrointestinal tract, prostate)." (PMID 29165379, 2017). "With respect to the association analysis, FGFR3 staining was significantly associated with a higher tumor grade (p < 0.01, Fisher’s exact test)." (PMID 28468611, 2017). "The altered RTKs in UC have been reported and associated with tumor cell proliferation and survival, including FGFR3 activation, EGFR amplification, ERBB3 mutation, and ERBB2 mutation or amplification." (PMID 27793038, 2016). "The calculated Cox regression model (including the potentially prognostic parameters grade, tumor stage, nodal status and metastasis) confirmed the clinical impact of FGFR3 mutation on recurrence-free survival." (PMID 27669755, 2016). "In particular, mutations in the TERT promoter and FGFR3 are the most frequently detected, with rates comparable to those of other studies and reflecting the situation in primary tumor tissue." (PMID 27611947, 2016). "In this case, the FGFR3-S249C mutation was detected from tumor FFPE tissue-derived genomic DNA by Ion AmpliSeq Cancer Hotspot Panel v2." (PMID 27930669, 2016). "In cancer, oncogenic aberrations of the FGFR3 gene cause sustained cell proliferation, contributing to tumor development." (PMID 26711175, 2016). "In the present study, we found that the FGFR-3 expression was significantly associated with tumor stage." (PMID 26465941, 2015). "Further the detection of FGFR-3 mutations in urine from patients with FGFR-3 mutations in primary tumor indicating tumor recurrence has also been reported." (PMID 26465941, 2015). "The number of cancers analysed by whole-genome sequencing was too low to reliably analyse associations between clinicopathological variables and specific mutations, although we noted that FGFR3 mutations were more common in pTa tumours, as expected." (PMID 24777035, 2014).